PUS10 (pseudouridine synthase 10)
Description:
Protein with different functions depending on its subcellular location: involved in miRNA processing in the nucleus and acts as a tRNA pseudouridylate synthase in the cytoplasm. In the cytoplasm, acts as a pseudouridylate synthase by catalyzing synthesis of pseudouridine(54) and pseudouridine(55) from uracil-54 and uracil-55, respectively, in the psi GC loop of a subset of tRNAs. tRNA pseudouridylate synthase activity is enhanced by the presence of 1-methyladenosine at position 53-61 of tRNAs. Does not show tRNA pseudouridylate synthase activity in the nucleus. In the nucleus, promotes primary microRNAs (pri-miRNAs) processing independently of its RNA pseudouridylate synthase activity. Binds pri-miRNAs. Modulator of TRAIL/TNFSF10-induced cell death via activation of procaspase-8 and BID cleavage. Required for the progression of the apoptotic signal through intrinsic mitochondrial cell death.
Synonyms: Hup10; CCDC139; DOBI; FLJ32312
Tractability: Small molecule: it has a binding pocket of medium quality. PROTAC: ubiquitination databases record sites on it.
Gene: Protein-coding gene on chromosome 2 (60,938,141 to 61,018,259, reverse strand). Ensembl gene ENSG00000162927.
Subcellular location: Nucleus; Cytoplasm; Mitochondrion
Subcellular location (Human Protein Atlas): Mitochondria; Nuclear bodies; Nucleoplasm
Gene Ontology:
Molecular function: primary miRNA binding; protein binding; pseudouridine synthase activity; tRNA pseudouridine synthase activity; tRNA pseudouridine(55) synthase activity; RNA binding
Biological process: primary miRNA processing; tRNA pseudouridine synthesis; pseudouridine synthesis; RNA modification
Cellular component: cytoplasm; cytosol; mitochondrion; nucleus
Genetic constraint (gnomAD): Loss-of-function variants: 27 observed, 34.69 expected, observed/expected ratio (o/e) 0.78, 90% interval 0.57 to 1.07. The upper end of that interval is the gene's LOEUF score, 1.07, which puts it in group 4 of 6, group 1 being the genes least tolerant of losing a copy. Missense variants: 386 observed, 347.02 expected, observed/expected ratio (o/e) 1.11, 90% interval 1.02 to 1.21. Synonymous variants: 120 observed, 117.39 expected, observed/expected ratio (o/e) 1.02, 90% interval 0.88 to 1.19.
Homologues: Orthologues: chimpanzee PUS10 (99% identical), macaque PUS10 (98% identical), dog PUS10 (95% identical), guinea pig PUS10 (92% identical), mouse Pus10 (87% identical), rat Pus10 (85% identical), rabbit PUS10 (78% identical), pig PUS10 (76% identical), tropical clawed frog pus10 (66% identical), zebrafish pus10 (57% identical), Drosophila melanogaster Pus10 (32% identical), Caenorhabditis elegans Y48C3A.20 (29% identical).
Diseases named in the same sentence as PUS10 in open-access papers:
PUS10 is named in the same sentence as 22 diseases in open-access papers, as found by Europe PMC text mining. Sharing a sentence is not in itself a finding about the gene and the disease. The quoted sentences say what the papers report.
lung carcinoma (4 papers, 2020 to 2025). "We supposed that rs9309336 may interfere with the expression of PUS10 and reduce the sensitivity of tumor cells to TRAIL, which in turn promoting tumor cells' immortality and the occurrence of lung cancer." (PMID 31956354, 2020). "PUS10 is a mediator of TNF-related apoptosis inducing ligand (TRAIL)-induced apoptosis in prostate cancer cells, and genomic alterations of PUS10 locus are significantly associated with lung cancer risk, although it is not clear whether this effects are dependent on pseudouridylase activity." (PMID 33461542, 2021).
prostate carcinoma (4 papers, 2017 to 2022). A carcinoma that arises from epithelial cells of the prostate gland. "PUS10 is present only in eukaryotes, and the dysregulation of PUS10 induces apoptosis in prostate cancer cells by reducing their sensitivity to the tumor necrosis factor-related apoptosis-inducing ligand." (PMID 36360287, 2022). "Moreover, the molecular mechanisms of PUS1 involvement in melanoma and breast cancer, and PUS10 involvement in prostate cancer have also been initially explored." (PMID 36437949, 2022).
celiac disease (3 papers, 2013 to 2022). An autoimmune genetic disorder with an unknown pattern of inheritance that primarily affects the digestive tract. "Researchers have been studied that IBD and celiac disease have the similar genetic background; IL18RAP, PTPN2, TAGAP, and PUS10 have been identified as shared risk loci for both CD and celiac disease." (PMID 36204317, 2022).
renal cell carcinoma (2 papers, 2023 to 2025). "PUS10 silencing was shown to promote renal cell carcinoma metastasis with a dramatically stronger bioluminescent signal." (PMID 37596681, 2023). "Herein, we investigated the role of PUS10 in renal cell carcinoma." (PMID 37596681, 2023). "In renal cell carcinoma cells, it has been shown that HIF-1 accumulation leads to downregulation of pseudouridine synthase 10 (PUS10), an enzyme responsible for converting uridine to pseudouridine (Ψ) in tRNA." (PMID 40102715, 2025).
clear cell renal cell carcinoma (1 paper, 2024). "In clear cell renal cell carcinoma, PUS10 inhibits RCC migration through the PUS10/miR-194-5p/NUDC/Cofilin1 pathway, and this effect is independent of its catalytic activity." (PMID 39247811, 2024).
Hodgkinlymphoma (1 paper, 2019). "In particular, recurrent gain/amplificationof the 2p15-p16.1 locus, where REL, BCL11A, PAPOLG,PUS10, and USP34 genes reside, is a common observationin different lymphoma types including classical Hodgkinlymphoma and transformedfollicular lymphoma." (PMID 31410080, 2019).
kidney cancer (1 paper, 2023). Primary or metastatic malignant neoplasm involving the kidney. "In addition, a pancancer analysis implied the relatively low expression of PUS10 in kidney cancer compared with other cancers." (PMID 37596681, 2023).
tumor (8 papers, 2017 to 2024). "The rs9309336 may interfere with PUS10 expression, thereby reducing the sensitivity of tumor cells to tumor necrosis factor-associated apoptosis-inducing ligand (TRAIL)." (PMID 36553648, 2022). "Furthermore, a study revealed that the genetic variant rs9309336 may interfere with PUS10 expression, reducing tumor cell sensitivity to tumor necrosis factor-related apoptosis-inducing ligand (TRAIL)." (PMID 39737343, 2024). "Furthermore, a linkage between the critical tumor microenvironment hallmark with malfunction of the forementioned metastasis inhibition mechanism was presented, as demonstrated by repressed expression of PUS10 due to hypoxia and HIF-1A." (PMID 37596681, 2023). "We found that PUS1, PUS7, and PUS10 maintained consistent copy number amplification in most tumor types." (PMID 39162904, 2024). "The strong correlation between the mRNA level of PUS10 and that of established microRNA biogenesis-associated proteins, such as DICER, DGCR8, AGO1 and AGO3, in KIRC tumor tissues hinted at the involvement of PUS10 in microRNA processing." (PMID 37596681, 2023). "Taken together, in this part, we inferred that PUS10 exerts its anti-tumour effect by promoting the maturation of miR-194-5p." (PMID 37596681, 2023). "By performing qRT‒PCR using our SRRSH RCC cohort specimen, we identified the downregulation of PUS10 in tumor tissue compared with adjacent normal tissue." (PMID 37596681, 2023). "By investigating clinical information, we identified a lower expression of PUS10 in patients with tumor metastasis." (PMID 37596681, 2023). "Using our SRRSH RCC specimens, we identified the downregulation of miR-194-5p and its coexpression with PUS10 in tumor tissues by performing qRT‒PCR." (PMID 37596681, 2023). "However, the expression pattern of PUS10 differed from that of other regulators in that it showed a stable negative correlation with enrichment of MYC_TARGETS_V2, which was validated in 20 tumor types." (PMID 39162904, 2024). "Furthermore, a higher frequency of tumor relapse in patients from PUS10 low expression group was revealed and Kaplan–Meier plotter analysis of the SRRSH RCC cohort disclosed that patients with decreased PUS10 expression had shorter disease free survival." (PMID 37596681, 2023). "To investigate whether PUS10 could act as a tumor suppressor in RCC, we silenced PUS10 in 786-O and Caki-1 cells using two siRNAs, and the knockdown efficiency was examined at the mRNA and protein levels." (PMID 37596681, 2023). "This outcome indicates that the pseudouridine produced by PUS10 might contribute little to its tumor-suppressing impact." (PMID 37596681, 2023). "rs9309336 may interfere with PUS10 expression, reducing tumor cell sensitivity to tumor necrosis factor-related apoptosis-inducing ligand (TRAIL)." (PMID 35484099, 2022). "Therefore, any defect in the movement or interactions of PUS10 would reduce the TRAIL sensitivity of tumor cells." (PMID 28981101, 2017). "In summary, we demonstrated the decreased expression of PUS10 in RCC tumors and determined that it is a tumor suppressor that inhibits cancer cell migration." (PMID 37596681, 2023). "Functionally, silencing PUS10 significantly promoted the migration of RCC cancer cells in vitro and in vivo, certifying its tumor suppressor role in RCC." (PMID 37596681, 2023). "We initially calculated the univariate and multivariate analysis of overall survival (OS) rate, including the expression of genes belonging to the PUS family (PUS1, PUS3, PUS7, PUS10, PUS7L, PUSL1), patients’ age, gender, race and Tumor Node Metastasis (TNM)-stage, and set grade as co-variate." (PMID 37315299, 2023).
cancer (3 papers, 2020 to 2023). A tumor composed of atypical neoplastic, often pleomorphic cells that invade other tissues. "Considering that mounting evidence has demonstrated the pivotal role of these small noncoding RNAs in regulating cancer development, it seems tempting to attribute the effect of PUS10 to the probable dysregulation of microRNAs in RCC." (PMID 37596681, 2023). "Parallel with these studies, we identified another factor in this process, PUS10, that blocks cancer cell migration in RCC by facilitating the maturation of a functional microRNA." (PMID 37596681, 2023). "Considering that mounting research has demonstrated the dysregulation of microRNAs and the crucial role they play in RCC, we speculated that PUS10 might influence cancer migration in a manner dependent on its downstream microRNAs." (PMID 37596681, 2023). "While RCC cancer cells originate from kidney tubular endothelial cells, our IHC results exhibited a dramatic contrast in PUS10 staining between these two types of cells, hinting that PUS10 possibly plays a significant role in the evolution of RCC." (PMID 37596681, 2023). "Expression quantitative trait loci analysis revealed that rs9309336 and rs17160062 could regulate the expressions of cancer-related genes (PUS10 and CHD1L)." (PMID 31956354, 2020). "The direction of our mechanism exploration is determined by an intriguing phenomenon: As overexpressing PUS10 dramatically inhibits cancer cell migration, ectopic expression of the mutant PUS10, whose RNA modification function is abrogated, could have a similar inhibitory effect." (PMID 37596681, 2023). "Finally, we found that HIF-1A signaling might result in the silencing of PUS10 in cancer." (PMID 37596681, 2023). "Here, we determined that the downregulation of PUS10 is at least partially induced by HIF-1A by transcriptional inhibition, thus providing another link between hypoxia and RCC cancer metastasis." (PMID 37596681, 2023). "According to our microRNA sequencing and online data, we revealed that PUS10 could facilitate the maturation of miR-194-5p and subsequently regulate NUDC/Cofilin1-dependent cytoskeleton dynamics to inhibit RCC cancer migration." (PMID 37596681, 2023). "For the first time, we provide insight into PUS10 in cancer progression, which is not reliant on its RNA modification catalytic activity." (PMID 37596681, 2023).
infection (1 paper, 2023). The state of being infected such as from the introduction of a foreign agent such as serum, vaccine, antigenic substance or organism. "Although MDV lacking pUS10 replicated and spread in experimentally infected chickens, it was less virulent implicating an important role of pUS10 in natural infection of the host." (PMID 36749787, 2023). "Thirdly, pUS10 may play a role in establishing infection during natural infection via the respiratory route." (PMID 36749787, 2023). "However, chickens naturally infected with pUS10-null virus had less disease induction, which warrants further studies on the role pUS10 may play during natural infection and disease induction." (PMID 36749787, 2023). "When expression of pUS10 was evaluated in cell culture and in FFE skin cells during in vivo infection, pUS10 was severely reduced or abrogated in cells infected with CHPK mutant or CHPK-null viruses, respectively, indicating a potential role for pUS10 in transmission." (PMID 36749787, 2023). "Interestingly, pUS10 is not required for transmission, contrary to former studies, but appears to be important for the development of MD during natural infection, potentiating a role for pUS10 in establishing infection and disease induction." (PMID 36749787, 2023).
PUS10 also shares sentences with these, for which no sentence is quoted: breast carcinoma (2 papers); alcohol dependence (1); alveolar rhabdomyosarcoma (1); B-cell lymphoma (1); Crohn disease (1); inflammatory bowel disease (1); influenza infection (1); lymphoma (1); melanoma (1); prostate adenocarcinoma (1); sarcoidosis (1); Zinc deficiency (1).